RNU1-97P (RNA, U1 small nuclear 97, pseudogene)
Gene: Small nuclear RNA gene on chromosome Y (23,740,942 to 23,741,105, reverse strand). Ensembl gene ENSG00000252681.
Homologues: Orthologues: chimpanzee U1 (99% identical), chimpanzee U1 (98% identical), chimpanzee U1 (97% identical), macaque U1 (79% identical). Paralogues in human: RNU1-40P (100% identical), RNU1-128P (87% identical), RNU1-95P (87% identical), RNU1-41P (85% identical), RNU1-48P (85% identical), RNU1-89P (84% identical), RNU1-1 (84% identical), RNU1-2 (84% identical), RNU1-27P (84% identical), RNU1-28P (84% identical), RNU1-3 (84% identical), RNU1-4 (84% identical), and 133 more.